IL13 (interleukin 13)
Diseases named in the same sentence as IL13 in open-access papers (continued):
Sharing a sentence is not in itself a finding about the gene and the disease.
airway hyperresponsiveness (continued). "At the molecular level, the HDM challenge elevated the expression of major Th2 cytokines (IL-4 and IL-13), IL-17a, and muc5ac, which are key mediators of airway hyperresponsiveness and mucus overproduction." (PMID 39682780, 2024). "IL-13 plays an important role in increased mucus production, goblet cell metaplasia and airway hyperresponsiveness." (PMID 39060923, 2024). "The overproduction of IL-13 has been proven to induce many common features of allergic pathologies, such as airway hyperresponsiveness, eosinophilic inflammation, and excessive mucus secretion." (PMID 38397126, 2024). "In the lung, they release IL-5 and IL-13 and activate eosinophilic lung accumulation, calcination, mucus aggregation, epithelial interstitial reaction, and finally pulmonary airway hyperresponse and airway remodeling." (PMID 39015676, 2024). "It has been shown that through the activation of IL-5 and IL-13 secretion, IL-33 promotes airway hyperresponsiveness." (PMID 37107767, 2023). "When they gave anti-TSLP monoclonal antibody, the DEHP enhanced airway inflammation, Th2 cytokines (IL-4, IL-5 and IL-13) production, and airway hyperresponsiveness were reduced via neutralized TSLP." (PMID 37545493, 2023). "Using IL-13 as a stressor, the authors observed the classical effects of IL-13 on the airways, such as airway hyperresponsiveness, eosinophilic inflammation, and mucus production." (PMID 37809717, 2023). "In allergic asthmatic mice, GPER agonist attenuated airway hyperresponsiveness, inflammatory cell accumulation, and Th2 cytokine production (IL-5 and IL-13) in BAL fluid." (PMID 36142703, 2022). "IL-13 elicits a broad spectrum of effector type 2 immune functions including eosinophilic inflammation, mucus secretion, and airway hyperresponsiveness." (PMID 35950748, 2022). "IL-4, and to a lesser degree IL-13, animate IgE synthesis; while IL-13 has a fundamental role in airway hyperresponsiveness, mucus production and airway remodeling." (PMID 35743783, 2022). "TSLP can stimulate the activation and proliferation of ILC2s to produce a large amount of IL-5 and IL-13, resulting in airway inflammation and airway hyperresponsiveness." (PMID 36482599, 2022). "Subsequently, a reverse genetic approach indicated that the fusion protein genes of the RSV line 19 strain were responsible for the lung production of IL-13 and airway mucus and airway hyperresponsiveness." (PMID 36077310, 2022). "Inhibition of IL-13 activity has been reported to prevent airway hyperresponsiveness, pulmonary eosinophilia, and mucus production." (PMID 35677382, 2022). "Using an airway hyperresponsiveness mice model, one study showed that PS-F2 inhibited airway hyperresponsiveness via reducing Th2 cytokines, interleukin (IL)-4, IL-5, and IL-13." (PMID 34681911, 2021). "In a mouse model of asthma, natural killer T cells (NKT) with a phenotype of CD4+IL-17RB+ are able to produce IL-13 and Th2 chemokines in response to IL-25 stimulation and therefore promote airway hyperresponsiveness." (PMID 34122457, 2021). "It has been demonstrated that TH2 cytokine IL-13 participates in airway inflammation, promotes airway hyperresponsiveness, induces mucosal metaplasia and chemokine expression, and plays an important role in airway remodeling." (PMID 32280354, 2020). "IL-5 promotes airway eosinophilia, IL-4 and IL-13 act directly on the airway epithelium to induce goblet cell metaplasia and mucus hypersecretion, and IL-13 mediates airway hyperresponsiveness by effects on airway smooth muscle cells." (PMID 33255348, 2020). "This is further seen in the therapeutic model where in the presence of a residual IL‐13 production, the protective effect against IL‐13 still remains with an observed diminished airway hyperresponsiveness." (PMID 31782803, 2020).
airway hyperresponsiveness (continued). "To examine the airway inflammatory changes occurring in IL-13 TG mice, we analyzed the extent of airway hyperresponsiveness (AHR) in their lung tissue samples and compared it with that of WT mice." (PMID 33046682, 2020). "In mice, IL-13 treatment induced airway hyperresponsiveness and led to increased numbers of IL-17-producing CD4+ T cells." (PMID 32849611, 2020). "Carbonic anhydrase II (CA2), which was negatively correlated with miR-26a-5p and significantly upregulated in exacerbated horses, is known to be upregulated by Th2 cytokines like IL-4 and IL-13, and reportedly promotes airway hyperresponsiveness." (PMID 32998415, 2020). "IL-13, IL-1 β, IL-6, IL-4, IL-5 are Th2 cell-type factors, mainly involved in mucus secretion, eosinophil production, IgE synthesis, and airway hyperresponsiveness." (PMID 31024302, 2019). "These pollutants and carbon nanotubes stimulate lung ILC2s, produce high levels of interleukin (IL)-5 and IL-13, and induce airway hyperresponsiveness." (PMID 31269777, 2019). "In the present study, T. IIA inhibited the infiltration of inflammatory cells in the lung, reduced the productions of IL-4, IL-5, and IL-13, and dampened airway hyperresponsiveness." (PMID 30834081, 2019). "The pollutants also stimulate ILC2 to produce IL-5 and IL-13, thereby increasing airway hyperresponsiveness." (PMID 31269777, 2019). "IL-4 was important in CD4+ lymphocyte differentiation and the production of IgE,while IL-13 drived airway hyperresponsiveness, mucus production, and subepithelial fibrosis." (PMID 31747880, 2019). "For example, decreases in miR-133a have been linked to increases in RhoA pathway activity in bronchiolar smooth muscle and airway hyperresponsiveness due to IL-13 or IL-17 treatment." (PMID 31511493, 2019). "IVE and AET ameliorated OVA-driven airway hyperresponsiveness (p < 0.01), pulmonary eosinophilic infiltration (p < 0.05), mucus hypersecretion (p < 0.01), and IL-4, IL-5, IL-13, and CCR3 production (p < 0.05), as well as IgE levels (p < 0.01)." (PMID 29062168, 2017). "Strikingly, administration of G-1 attenuated airway hyperresponsiveness, accumulation of inflammatory cells, and levels of Th2 cytokines (IL-5 and IL-13) in BAL fluid." (PMID 25826377, 2015). "IL-13 is important in inducing many of the characteristics of allergic airway disease, including airway hyperresponsiveness, goblet cell hyperplasia, and mucus secretion." (PMID 25426119, 2014). "Introduction of exogenous IL-13 into murine airways resulted in lymphocytic and eosinophilic inflammation, airway remodeling, and airway hyperresponsiveness (AHR)." (PMID 23841068, 2013). "Treatment with anti-CD4 monoclonal antibody or deletion of the IL-13 gene improves ovalbumin-induced airway hyperresponsiveness and reduces airway inflammatory cells in transgenic mice." (PMID 23382928, 2013). "Th2-driven cytokines, interleukin (IL)-4 and IL-13, trigger B cells to synthesize IgE, while IL-5 plays a role in eosinophil maturation and survival, and IL-13 regulates airway hyperresponsiveness and mucus hyperplasia." (PMID 22523502, 2012). "Although both compounds inhibit chitinase activity in vivo, only demethylallosamidin treatment reduces allergen or IL-13-induced airway hyperresponsiveness." (PMID 21609838, 2011). "In the ovalbumin-sensitized animal model of inflammation and airway hyperresponsiveness, β-agonist- promoted relaxation of methacholine constricted airways is decreased compared to that in control mice, which is also found in the IL-13 overexpression model." (PMID 21611147, 2011). "Previous research has highlighted the importance of IL-13 in controlling airway hyperresponsiveness in mice." (PMID 20573261, 2010). "Studies in mouse models have also suggested that IL-13 can modulate airway hyperresponsiveness by increasing the response of airway smooth muscle cells to specific bronchoconstrictors." (PMID 20205953, 2010).
airway hyperresponsiveness (continued). "At the physiological level, biologic therapies contribute to the reduction in type 2 inflammation by targeting specific cytokines (IL-4, IL-5, IL-13) and IgE, leading to decreased airway hyperresponsiveness, reduced mucus production, and improved lung function." (PMID 41302212, 2025). "ILC2s not only mediate eosinophil aggregation, goblet cell metaplasia, and airway hyperresponsiveness through the production of IL-5, IL-9, and IL-13 but also may act as APCs to provide CD4 + T lymphocytes with MHCII molecules and OX40 ligands (OX40L)." (PMID 39060923, 2024). "Activation of the IL-4/IL-13 pathway promotes profound airway hyperresponsiveness." (PMID 37214308, 2023). "In an animal model of acute allergic asthma, addition of CD200R ligand intratracheally before allergen challenge reduces airway hyperresponsiveness, IL-13 levels in bronchoalveolar lavage (BAL), and lung dendritic cell accumulation, without reducing eosinophil recruitment." (PMID 36591265, 2022). "Indeed, IL-4 promotes both Th2 cell differentiation and biosynthesis of immunoglobulins E (IgE), whereas IL-13 is mostly responsible for airway hyperresponsiveness, mucus overproduction, and bronchial structural changes." (PMID 35350765, 2022). "Activated IL-13 and IL-9 can promote allergen-induced airway hyperresponsiveness." (PMID 35744915, 2022). "Our results showed that lonicerin significantly reduced airway hyperresponsiveness the number of inflammatory cells (especially eosinophils) and the elevation of interleukin (IL)-4, IL-5, IL-13 and eotaxin in bronchoalveolar lavage fluid (BALF) supernatants of mice." (PMID 36618942, 2022). "In addition, airway eosinophils are activated by IL-5 to promote degranulation, and airway hyperresponsiveness, inflammation, and remodeling are affected by IL-13." (PMID 36296620, 2022). "Increased airway hyperresponsiveness after EC vapor inhalation.Increased infiltration of inflammatory cells, including eosinophils, into airways from blood.Stimulation of production of Th2 cytokines such as IL-4, IL-5 and IL-13 and allergen-specific IgE." (PMID 34442368, 2021). "It should be mentioned that the source of IL-13 in allergen-induced airway hyperresponsiveness may depend on the age of first exposure, with IL-13+ CD4+ T cells dominating in neonatal life and IL-13+ ILC2s dominating in adult mice." (PMID 34868033, 2021). "Additionally, in mice sensitised with ovalbumin, neutralisation of IL-13 inhibited airway hyperresponsiveness, goblet cell metaplasia, and lung eosinophilia." (PMID 34439751, 2021). "Notably, combined blockade of type 2 cytokine IL-13 and IL-25 was even more effective than blockade alone in reducing infiltration of inflammatory cells in the airways with attenuated airway hyperresponsiveness and tissue remodeling." (PMID 34122457, 2021). "In addition, it also induced eosinophilic inflammation, the production of IL-4, IL-5, IL-13, and IL-33 in bronchoalveolar lavage fluid, and airway hyperresponsiveness." (PMID 34079051, 2021). "We illustrate its utility in a prolonged model of IL-13-induced airway hyperresponsiveness." (PMID 32296115, 2020). "IL-13 treatment induced airway hyperresponsiveness to MCh as early as day 5 (F = 5.097, p = 0.03)." (PMID 32296115, 2020). "In addition, matrine inhibits ovalbumin-induced airway hyperresponsiveness, inflammatory cell infiltration, and goblet cell differentiation via regulating Il-4, IL-13, and TNF-α expression." (PMID 30800071, 2019). "On the contrary, in mice receiving intranasal exposure of high-dose HDM at early time points and multiple treatments of low-dose HDM at later time points, HRV triggers both type 1 and type 2 responses including IL-4 and IL-13 expression, eosinophilic inflammation and airway hyperresponsiveness." (PMID 30513770, 2018). "IL-13 directly induces mucus hypersecretion and airway hyperresponsiveness." (PMID 29910732, 2018).
airway hyperresponsiveness (continued). "Cytokines such as IL-13 or TNF-α caused significantly lower inflammation and hyperresponsiveness in the CD38 KO mice compared to WT controls, suggesting the crucial roles of CD38 in the contractility of airway smooth muscle and airway hyperresponsiveness." (PMID 30619097, 2018). "The fusion (F) gene of Line 19 strain has been identified as a mucogenic virulence factor and a recombinant virus rA2-Line 19F, carrying fusion (F) gene from the Line 19 strain induces airway hyperresponsiveness, mucus metaplasia and IL-13 expression as Line 19 does." (PMID 30513770, 2018). "In the present study, we provide evidence that IL-33 exacerbates antigen-induced asthmatic responses, including airway hyperresponsiveness, inflammation and remodeling, mast cell activation, production of IgE and cytokines including IL-4, IL-5 and IL-13, and accumulation of pulmonary ILC2s." (PMID 28652606, 2017). "T helper type 2 immune responses such as high levels of IL-4 versus IFN-γ and the release of IL-5 and IL-13 cytokines are known to contribute to eosinophil recruitment to the lung, goblet cell formation from epithelial cells, mucus production and airway hyperresponsiveness." (PMID 25658239, 2015). "We previously found that, in OVA-sensitized and -challenged mice with allergic airway inflammation, RV infection increases eotaxin-1, IL-4 and IL-13 production from alternatively-activated (M2 polarized) airway macrophages, further enhancing eosinophilic inflammation and airways hyperresponsiveness." (PMID 24907978, 2014). "IL-13 is also the primary Th2 cytokine in induction of airway hyperresponsiveness." (PMID 23451035, 2013). "The Th2 cytokine, IL-13, may play a key role in increasing airway hyperresponsiveness (AHR), eosinophilic pulmonary inflammation, goblet cell metaplasia, and lung fibrosis." (PMID 23382928, 2013). "Treatment of mice with the C. elegans crude extract significantly decreased methacholine-induced airway hyperresponsiveness and the total cell counts and levels of IL-4, IL-5 and IL-13 in the bronchoalveolar lavage fluid but increased the levels of IFN-γ and IL-12." (PMID 22558152, 2012). "Moreover, inhibition of IL-13 efficiently reduced HDME/LPS-induced airway hyperresponsiveness and inflammation and could be used to bypass CS-resistance." (PMID 39157265, 2024). "On the contrary, the combined blockade of type 2 cytokines, namely, IL-13 and IL-25, was more effective than the obstruction of either cytokine in reducing the infiltration of inflammatory cells in the airways with attenuated airway hyperresponsiveness and tissue remodeling." (PMID 36834723, 2023). "Some studies speculated that IL-13 could promote allergen-induced airway hyperresponsiveness." (PMID 35887565, 2022). "In our study we used a human-based ex-vivo organ tissue to assess the effect of IL-13 in comparison to commonly used laboratory animals and in-vitro cell cultures based on clinically relevant endpoints such as mucus hypersecretion, inflammation, and airway hyperresponsiveness." (PMID 30500834, 2018). "Thus, the lower level of IL-10 and IL-13 may contribute to the mild airway hyperresponsiveness in March1−/− compared to WT mice." (PMID 29854835, 2018). "Therefore, one explanation to our results is that our read-out time point at 48h to acquire the highest response in HDM-induced airway hyperresponsiveness (based on our unpublished data) may occur later than the peak of IL-5 and IL-13 production in lung." (PMID 26214807, 2015). "Prebiotic intervention significantly reduced airway hyperresponsiveness (AHR) and type 2 cytokines (IL-4, IL-5, IL-13) and various cell counts, including neutrophil, macrophage, lymphocyte, eosinophil, and total bronchoalveolar (BALF)." (PMID 41754200, 2026). "Compared to WT mice, NLRP3-/- mice displayed significantly increased airway hyperresponsiveness (AHR), mucus production, and elevated systemic levels of IL-5 and IL-13." (PMID 41394833, 2025).
airway hyperresponsiveness (continued). "With the addition of microcapsules, the bread effects were more pronounced, with a significant reduction in airway hyperresponsiveness, percentage of eosinophils, and Th2 cytokines concentrations (IL5 and IL13), and an increase in the IL17A concentrations." (PMID 38655128, 2024). "Then airway hyperresponsiveness (AHR), eosinophil percentage, levels of interleukin (IL)‐33, IL‐25, IL‐13, IL‐5, IL‐4, total and ovalbumin (OVA)‐specific immunoglobulin (Ig)E, and lung histopathology were evaluated." (PMID 38664220, 2024). "Most importantly, intratracheal instillation of shikonin can down-regulate the release of IL-4, IL-5, IL-13, and TNF-α in BALF and reduce pulmonary eosinophils and airway hyperresponsiveness." (PMID 39444792, 2024). "IL-5, IL-13, and ovalbumin (OVA) specific IgE and airway hyperresponsiveness (AHR) are also responsible for mitochondrial dysfunction and thus conclude that Th2-dominant response enhances mitochondrial oxidative stress in airways." (PMID 35796922, 2022). "A study showed that IL-18 induced airway hyperresponsiveness and lung fibrosis by IFN-γ and IL-13 production." (PMID 34367377, 2021). "The results demonstrated that matrine alleviated eosinophil infiltration, airway hyperresponsiveness (AHR), and airway inflammation by inhibiting Th2 cytokines or the IL-4/IL-13/STAT-6 pathway in asthmatic mice." (PMID 33041782, 2020). "In Tlr9–/– mice, airway hyperresponsiveness (AHR) and the number of eosinophils decreased, and production of the Th2 cytokines IL-13, IL-5, and IL-4 was suppressed, compared with in wild-type mice." (PMID 33093516, 2020). "It has been reported that MT inhibited ovalbumin (OVA)-induced airway hyperresponsiveness (AHR) in mice by decreasing the production of IL-4 and IL-13, and increasing the expression of interferon (IFN)-γ." (PMID 33041782, 2020). "HD strongly reduced goblet cell hyperplasia, eosinophil infiltration, and reactive oxygen species (ROS), which reduced airway hyperresponsiveness (AHR), inflammation, and the expression of Th2 cytokines (IL-5 and IL-13) in bronchoalveolar lavage fluid (BALF)." (PMID 30823378, 2019). "Airway hyperresponsiveness as well as levels of IFN-γ, IL-13, IL-6, and IL-10 was lower in the lungs of asthmatic March1−/− mice compared to WT, whereas lung levels of TNF-α, IL-4, and IL-5 were not significantly different." (PMID 29854835, 2018). "Following OVA sensitization, HRV infection triggers eosinophilic inflammation and airway hyperresponsiveness, along with increased expression of mucins (Muc5AC and Muc5B), eotaxin-1/CCL11, IL-4 and IL-13." (PMID 30513770, 2018). "In neonatal mice A alternata exposure induced higher serum IgE levels, pulmonary IL-33 levels, and IL-13+ innate lymphoid cell (ILC) and TH2 cell numbers but similar airway hyperresponsiveness (AHR) compared with those after house dust mite exposure." (PMID 25746970, 2015). "In vivo, intratracheal administration of CD86 siRNA during OVA challenge reduced the production of IL-5, IL-13, and TARC release and ameliorated airway eosinophilia, airway hyperresponsiveness, and elevation of OVA-specific IgE." (PMID 25344652, 2014). "This was determined by the use of IL-13−/− eosinophils that were adoptively transferred by intravenous injection into Δdbl-GATA mice, which exhibited low airway hyperresponsiveness." (PMID 25426119, 2014). "Compared to WT, T-cad−/− mice were protected against OVA-induced airway hyperresponsiveness, increases in BAL inflammatory cells, and induction of IL-13, IL-17, and eotaxin expression." (PMID 22815927, 2012). "IgG-treated animals exhibited attenuated allergen-induced production of IgE, IL-4, and IL-13, along with impaired OVA-induced goblet cell hyperplasia and Muc5ac expression and suppressed airway hyperresponsiveness, consistent with a shift away from a Th2 response." (PMID 40725026, 2025).